DEPDC1B (DEP domain containing 1B)
Diseases named in the same sentence as DEPDC1B in open-access papers (continued):
Sharing a sentence is not in itself a finding about the gene and the disease.
tumor (continued). "Significant differences were observed in the DEPDC1B expression between the normal and tumor stage/grade cells." (PMID 35095994, 2021). "Collectively, DEPDC1B knockdown induces cell apoptosis, leads G2 phase arrest, and inhibit growth and migration in tumor mediated by CDK1." (PMID 34032605, 2021). "Functional assays revealed that DEPDC1B enhanced the migration, invasion, and proliferation of PCa cells in vitro and promoted tumor metastasis and growth in vivo." (PMID 33135357, 2020). "Tumor size was measured in the animals over time and tumor volume was calculated accordingly; these data indicated that tumor growth was significantly suppressed by DEPDC1B KD (P < 0.001)." (PMID 33203836, 2020). "The analysis of Cohort 2 also demonstrated that a high level of DEPDC1B positively correlated with a high Gleason score (P = .002), advanced pathological tumor stage (P<.001), and a high incidence of LN metastasis (P = .022)." (PMID 33135357, 2020). "First, results of IHC shown that the expression of DEPDC1B in the tumor tissues was significantly higher than that in the normal tissues." (PMID 32684847, 2020). "Based on Mann–Whitney U analysis, we found that the significant correlation between DEPDC1B expression and pathological grading as well as tumor recurrence." (PMID 32684847, 2020). "The data suggested that when DEPDC1B was expressed in cells, cellular motility was stimulated and invasion ability in tumor cells increased." (PMID 25091805, 2014). "Similarly, DEPDC1B autoantibody was also found to decrease in the BM subjects, and it recovered to a higher level after tumor resection." (PMID 39949782, 2025). "In conclusion, our study reveals that, in contrast to its role in other cancers, DEPDC1B may function as a tumor suppressor gene in COAD, impeding the proliferation of COAD cells." (PMID 39087856, 2024). "In summary, these results suggest that DEPDC1B may play a role in the immune response within the tumor immune microenvironment." (PMID 39087856, 2024). "The impact of DEPDC1B on the tumor immune microenvironment remains unexplored." (PMID 39087856, 2024). "Experimental results from our study, demonstrating that DEPDC1B knockdown promotes the proliferation of COAD cells, support the hypothesis that DEPDC1B may function as a tumor suppressor in COAD." (PMID 39087856, 2024). "However, the role of DEPDC1B in the infiltration of the tumor immune microenvironment (TIME) remains unexplored." (PMID 39087856, 2024). "Our objective was to investigate whether DEPDC1B functions as a tumor suppressor gene in COAD by influencing the immune microenvironment of tumors." (PMID 39087856, 2024). "We further explored the effect of interference with DEPDC1B expression on tumor metastasis in vivo." (PMID 37642235, 2023). "As expected, interference with DEPDC1B expression hindered tumor metastasis." (PMID 37642235, 2023). "Furthermore, the correlation of DEPDC1B expression and tumor characteristics in ESCC patients were analyzed with Mann–Whitney U analysis." (PMID 35706026, 2022). "The overlapping expressions of SOX10 and DEPDC1B in patient samples and in the tumor nodules prompted us to investigate whether SOX10 regulates DEPDC1B expression." (PMID 35088579, 2022). "Relationship between DEPDC1B expression and tumor characteristics in patients with CCA." (PMID 36568241, 2022). "Herein, DEPDC1B was identified as a tumor promotor in CCA, the knockdown of which could inhibit CCA development." (PMID 36568241, 2022). "Moreover, the smaller volume and weight of the solid tumors in the shDEPDC1B group also suggested that tumor growth slowed down when DEPDC1B was silenced (P < 0.01)." (PMID 36568241, 2022). "Moreover, Ki-67 expression was significantly decreased in the shDEPDC1B group compared with the shCtrl group, indicating that DEPDC1B knockdown attenuated the proliferative ability of tumor cells in mice." (PMID 35706026, 2022).
tumor (continued). "This is in line with a relatively low level of SCUBE3 expression in DEPDC1B+ primary tumor samples." (PMID 35088579, 2022). "Upregulation of DEPDC1B is inversely linked with patient survival in NSCLC and may increase tumor cell motility and invasion by activating Wnt/b-catenin signaling and functioning as a potential biomarker." (PMID 36530971, 2022). "In bladder cancer, DEPDC1B is a tumor promotor through targeting SHC1." (PMID 34330893, 2021). "Moreover, a xenograft model was constructed to research functions of DEPDC1B in tumor growth in vivo." (PMID 34032605, 2021). "Consistently, decreased expression of DEPDC1B suppressed tumor growth in xenograft mice." (PMID 34330893, 2021). "Taken together, DEPDC1B facilitates metastasis and tumor growth of PCa cells in vivo." (PMID 33135357, 2020). "The results proved that DEPDC1B was significantly upregulated in tumor tissues, and silencing DEPDC1B could inhibit proliferation, migration and promote apoptosis of GBM cell." (PMID 32684847, 2020). "Additionally, the results of immunohistochemical detection in the tumor tissues showed that the expression of Ki67 in shDEPDC1B group was lower than that in shCtrl group (P < 0.05), indicating that downregulation of DEPDC1B can inhibit tumor proliferative activity in mice." (PMID 34330893, 2021). "Finally, we indicated that knockdown of DEPDC1B significantly inhibited tumor growth in vivo." (PMID 32684847, 2020). "Moreover, DU145 and PC3 cells were embedded in Matrigel for 3D culture, which mimics the process of tumor invasion in the basement membrane, and we also found that DEPDC1B ablation inhibited the invasive capability, while overexpressing DEPDC1B accelerated invasion of PCa cell." (PMID 33135357, 2020). "We still wondered whether knockdown of DEPDC1B affects tumor growth in vivo." (PMID 32684847, 2020). "Among them, the expression of TIPRAP, WSCD1, TCP11L2, DPP4, CAB39 and PDPK1 were down-regulated, while PARP1, DEPDC1B, CKAP2, ORMDL2, MRPL44, POLD4 and TMEM187 were increased in tumor group." (PMID 39949782, 2025). "Functionally, knockdown of DEPDC1B inhibited ESCC cell proliferation, clone formation, migration, tumor formation and promoted apoptosis." (PMID 35706026, 2022). "We found that knockdown of DEPDC1B inhibited ESCC cell proliferation, clone formation, migration, tumor formation and promoted apoptosis." (PMID 35706026, 2022). "Here, we discovered a novel PCa metastasis oncogene, DEP domain containing 1B (DEPDC1B), which was positively correlated with the metastasis status, high Gleason score, advanced tumor stage, and poor prognosis." (PMID 33135357, 2020). "The expression levels of DEPDC1B were significantly higher in DEPDC1Btumor tissues than normal tissues (P < 0.001) and were also higher in grade III tumor tissues than in grade II tumor tissues." (PMID 33203836, 2020). "DEPDC1B plays a regulatory role by functioning as a GEF that activates Rac1 proteins and triggers migration in normal cells and invasion in tumor cells." (PMID 25091805, 2014). "Additionally, in LUAD, TCP11L2 was the only protein decreased in the tumor samples, and in LUSC, CAB39, DEPDC1B, DPP4, PDPK1, and POLD4 were significantly down-regulated." (PMID 39949782, 2025). "Moreover, knockdown of DEPDC1B inhibited ESCC cell proliferation, clone formation, migration, tumor formation and promoted apoptosis." (PMID 35706026, 2022). "According to IHC scores, DEPDC1B was highly expressed in 51.9% of tumor tissues but not in normal tissues (p < 0.001)." (PMID 35706026, 2022). "A correlation analysis between DEPDC1B expression and the clinical parameters of patients with CCA revealed that DEPDC1B expression was significantly upregulated in patients with a more advanced tumor grade (P < 0.05); these findings were further verified by Spearman rank correlation analysis." (PMID 36568241, 2022).
cancer (18 papers, 2014 to 2024). A tumor composed of atypical neoplastic, often pleomorphic cells that invade other tissues. "Aberrant expression of DEPDC1B (DEP domain-containing protein 1B) has been shown to be associated with various types of malignant tumors." (PMID 37056386, 2023). "The results of immunohistochemistry revealed that DEPDC1B was overexpressed in HCC tissues compared with para-carcinoma tissues, and the expression level of DEPDC1B was significantly associated to the pathological stage of tumors and T stage (P <0." (PMID 34032605, 2021). "DEPDC1B is a DEP domain-containing protein that has been found to be associated with a variety of human cancers." (PMID 33203836, 2020). "Increasing evidence suggests that DEPDC1B is associated with various types of human cancers." (PMID 35095994, 2021). "Conclusively, DEPDC1B may be an independent risk factor for OS among LIHC cancer patients and may be used as an early diagnostic marker in patients with LIHC." (PMID 35095994, 2021). "However, the understanding of the relationship between DEPDC1B and human cancers and the underlying mechanism was still in shortage." (PMID 33203836, 2020). "Most previous studies have consistently reported upregulated DEPDC1B expression in various cancer types, correlating with poor patient prognosis." (PMID 39087856, 2024). "Overall, our findings suggest a complex and context‐dependent role for DEPDC1B in cancer, urging further exploration of its clinical significance and functional mechanisms in COAD." (PMID 39087856, 2024). "DEPDC1B plays an important role in a variety of cancers, such as liver cancer, chordoma, pancreatic cancer, and non-small-cell lung cancer." (PMID 37642235, 2023). "Previous studies have shown that DEPDC1B is highly expressed in a variety of cancers, and its role is mainly related to regulating the cell cycle, promoting cell proliferation, invasion, and metastasis, and inhibiting apoptosis." (PMID 37642235, 2023). "Actually, research concerning the expression and mechanism of DEPDC1B in human cancers was still very limited and needs further investigation." (PMID 37056386, 2023). "Given that DEPDC1B plays a key role in multiple cancers, the role of this molecule in ESCC was explored to identify potential targets for ESCC patients." (PMID 35706026, 2022). "Unexpectedly, a latest article published in 2021 also suggested that overexpressed DEPDC1B played a role in promoting cancer in HCC." (PMID 34983303, 2022). "Extensive studies have shown that DEPDC1B is highly expressed in a variety of cancers and has a cancer-promoting effect." (PMID 34983303, 2022). "If CDK1 was knockdown, the pathway of DEPDC1B would be inhibited or blocked, which was consistent the results in other cancers." (PMID 34032605, 2021). "Furthermore, high DEPDC1B expression may be significantly associated with various cancers." (PMID 35095994, 2021). "Furthermore, the high expression of DEPDC1B may be associated with various cancers." (PMID 35095994, 2021). "The results of experiments showed that DEPDC1B knockdown of DEPDC1B inhibited cell proliferation and migration, which is consistent with other reports involving functions of DEPDC1B in other cancers." (PMID 34032605, 2021). "DEPDC1B is overexpressed in many cancers, where it promotes their proliferation, migration and invasion." (PMID 31825138, 2020). "DEPDC1B is overexpressed in several cancers with expression inversely correlated with patient survival." (PMID 31825138, 2020). "The overexpression of DEPDC1B in cells promotes cell migration and induces cell invasion in cancer cell lines." (PMID 25091805, 2014). "Numerous evidence suggested that DEPDC1B plays a key role in cancers, which may be a potential biomarker and therapeutic target." (PMID 35706026, 2022).
cancer (continued). "DEPDC1B could regulate RAC1 activity by increasing GTP loading in RAC1 instead of affecting Rho A activities in normal or cancer cells." (PMID 35095994, 2021). "The study strongly suggests an additional pathway of DEPDC1B to induce carcinoma." (PMID 35095994, 2021). "Knockdown of SHC1 in DEPDC1B-overexpressed cancer cells could abolish the promotion effects induced by DEPDC1B." (PMID 33203836, 2020). "Therefore, DEPDC1B may be a key regulator of cancer progression, and the detection of its expression level had important clinical value for diagnosis and prognosis of patients." (PMID 35706026, 2022). "Knockdown of SHC1 could alleviate the cancer-promoting effect of DEPDC1B on BC." (PMID 34187252, 2021). "The downstream of DEPDC1B, KIF23, is a member of kinesin motor protein involved in the regulation of cytokinesis and acts as an important regulator in cancer biology." (PMID 34983303, 2022). "We found that DEPDC1B regulated Rac1 activities by increasing GTP loading in Rac1 did not affect Rho A activities in either normal or cancer cells." (PMID 25091805, 2014). "The results indicated that DEPDC1B was able to promote cancer cell proliferation in nonadherent conditions." (PMID 25091805, 2014). "In addition, our experiments found that DEPDC1B expression levels in the experimental HCC cells were all overexpressed compared with the normal epithelial cells, which was in line with the high expression in other cancers from previous studies." (PMID 34983303, 2022).
infection (3 papers, 2021 to 2024). The state of being infected such as from the introduction of a foreign agent such as serum, vaccine, antigenic substance or organism. "The expression of DEPDC1B in HCT116 cells was effectively reduced by establishing stable cell lines through shRNA infection." (PMID 39087856, 2024). "The fluorescence of cells, which were infected with LV- NC(OE+KD), DEPDC1B+NC(KD), shCDK1+NC(OE), and DEPDC1B+shCDK1 for 72 h, observed by microscope demonstrates a >80% efficiency of infection." (PMID 34032605, 2021). "Moreover, MUG-Chor1 cells not only had high infection efficiency, but also the protein level of BIRC5 and DEPDC1B was significantly downregulated, which indicated that BIRC5 and DEPDC1B was knocked down successfully." (PMID 34330893, 2021).
DEPDC1B also shares sentences with these, for which no sentence is quoted: glioblastoma (5 papers); soft tissue sarcoma (3); cervical cancer (2); ovarian carcinoma (2); pancreatic ductal adenocarcinoma (2); atopic dermatitis (1); cholangiocarcinoma (1); esophageal cancer (1); gastric cancer (1); heart failure (1); multiple myeloma (1); nevus (1); prostate tumor (1).